FADD (Fas associated via death domain)
Diseases named in the same sentence as FADD in open-access papers (continued):
Sharing a sentence is not in itself a finding about the gene and the disease.
tumor (continued). "Control cells would be balanced in terms of FADD-mediated apoptosis and proliferation, with FADD levels enabling them for both functions, whereas tumor cells from the Low sub-group would be incompetent both for FADD-mediated apoptosis and proliferation, thus resulting in less aggressive tumors." (PMID 27556297, 2016). "But also, our results indicate that different statuses of FADD phosphorylation may be a key element providing the basis for tumor stratification." (PMID 27556297, 2016). "The resultant balance between FADD-dependent apoptotic and proliferative capacities may define the outcome of the tumor." (PMID 27556297, 2016). "Next, we try to tumor-specifically deliver FADD and N-FADD in vivo." (PMID 27767039, 2016). "In this study, the NirB promoter was designed to express FADD or N-FADD protein in tumor tissue." (PMID 27767039, 2016). "These similar findings suggest that ixazomib and bortezomib may both initiate tumor cell death through activation of the extrinsic pathway of apoptosis via FADD-induced caspase-8 activation." (PMID 27783987, 2016). "High FADD expression was observed in 21 of 30 (70%) of tumor tissues compared with adjacent histologically normal tissues, suggesting elevated FADD expression might contribute to tumor development." (PMID 27013580, 2016). "After adjusting for age at diagnosis, primary tumor status, lymph node status and tumor differentiation by multivariate Cox regression, patients with FADD gene amplification or high protein expression had the worst DFS (P = 0.028, HR = 1.483, 95% CI, 1.044–2.106)." (PMID 27764170, 2016). "On the other hand, FADD reduction has been reported in different tumor types." (PMID 27556297, 2016). "On the other hand, the differential accumulation of DN cells in tumors from the Moderate and Low sub-groups suggests that FADD might intervene in the differentiation and proliferation of tumor thymocytes, but these processes would be uncoupled." (PMID 27556297, 2016). "In addition, we observe a reduction of FADD phosphorylation that inversely correlates with the proliferation capacity and tumor aggressiveness." (PMID 27556297, 2016). "It will also be important to investigate whether cFLIP and FADD can enhance anti-tumor immunity considering that they have the potential to down-regulate Treg cells, which constitute a major obstacle for tumor immunotherapy." (PMID 25807052, 2015). "The earliest gene therapies involving FADD centered on anti-tumor and immunomodulative therapies." (PMID 24058479, 2013). "However, our present study contains mainly high T-stage tumour and the univariate significance of cyclin D1 and FADD implies a link to amplification." (PMID 18268491, 2008). "Considering the different functions of cortactin, cyclin D1 and FADD it would be interesting to see whether these genes, coamplified in the same tumour, have a function at specific stages of tumorigenesis." (PMID 18268491, 2008). "NFKB is activated TRADD-, TRAF3- and FADD-dependently and also plays a key role in the survival of tumor cells by inducing expression of anti-apoptotic genes such as Bcl2, Bcl2l1, vascular endothelial growth factor (VEGF), and X-linked inhibitor of apoptosis (XIAP)." (PMID 19077262, 2008). "Better knowledge of the mechanisms leading to regulation of FADD functions will improve understanding of tumor growth and the immune escape mechanisms, and could open a new field for therapeutic interventions." (PMID 15717929, 2005). "Indeed, TRAIL or Apo-2L, a member of the TNF family, induces apoptosis preferentially in tumour cells also through binding to its cognate death receptors and recruitment of FADD." (PMID 15138489, 2004). "Therefore, FADD has emerged as a promising new target for tumor immunotherapy." (PMID 37671047, 2023).
tumor (continued). "Interestingly we found that CDKN2A,FADD,GATA3,MYC were highly variable between gain and loss in CNV, while at the mRNA expression level these same NRGS were also found to be significantly different in normal tissues compared to tumor tissues." (PMID 35478725, 2022). "Together with the observation that silencing TRAIL-R2, FADD or Caspase-8 expression inhibits apoptosis induced upon glutamine limitation, all these findings point to a crucial role of the extrinsic pathway of apoptosis in tumor cell death under conditions of amino acids shortage." (PMID 36302756, 2022). "However, FADD can also contribute to anti-inflammatory responses of some non-tumor cell lines." (PMID 36348274, 2022). "And HIPK3 may exert its tumor suppressive potential through phosphorylation of FADD." (PMID 35096570, 2021). "Briefly, these results indicated that treatment with ADT-OH in combination with VNP-FADD significantly increased the protein level of FADD in tumour tissues and then induced apoptosis, thereby inhibiting tumour growth and improving the survival rate of tumour-bearing mice." (PMID 31949127, 2020). "Depletion of FADD protein action may lead to failure of apoptosis and, thus, to tumor development." (PMID 33076854, 2020). "Similarly, TNFα, RIP1, c-FLIP, and FADD may serve important roles in contributing to SM resistance in tumor cell lines." (PMID 32325691, 2020). "Altogether, FADD reduction may result in diminished apoptosis of tumor thymocytes." (PMID 27556297, 2016). "Moreover, immunofluorescence stained with anti-FADD (N-term) antibody revealed that the recombinant proteins were preferentially expressed in the necrotic areas of the tumors, suggesting that FADD and N-FADD proteins were efficiently expressed in tumor hypoxia regions." (PMID 27767039, 2016). "Recently, studies have demonstrated that FADD plays a crucial role in cell growth by interacting with the adenylate kinase 2 (AK2)/dual-specificity phosphatase 26 (DUSP26) protein complex and could be associated with tumor cell differentiation." (PMID 27764170, 2016). "Therefore, tumor cells that express a Ser 194 FADD mutant that cannot be phosphorylated or are unable to phosphorylate FADD at this Ser position are expected to resist apoptosis induced by anticancer drugs that induce G2/M arrest, and to be insensitive to the synergistic effect of chemotherapy." (PMID 15717929, 2005). "The heterogeneous expression of FADD and RIPK1 exacerbates the restriction of interaction and subsequent signaling in diverse tumor types." (PMID 38542202, 2024). "It promotes tumor cell migration and inhibits Fas induced apoptosis by assembling caspase-8/RIPK1/FADD/cFLIP complex." (PMID 37171396, 2023). "FADD was significantly overexpressed in LUAD, and patients with higher expression levels of FADD had a worse prognosis and more advanced tumor stage." (PMID 37671047, 2023). "Given the heterogeneity of HNSCC tumor cells, we evaluated amplification rates of ARGs and discovered that FADD and CTTN were often amplified in HNSCC tumor cells." (PMID 37682196, 2023). "In tumor tissues, the staining intensity of the target genes was strong (BID, HPRT1, SMN1), high (PGAM5), or medium (FADD, KIAA1191)." (PMID 37760507, 2023). "Several genes were found at lower expression levels in tumor cases, such as AXL, BAHC2, CFLAR, and DNMT1 while others were overexpressed such as BNIP3, DIABLO, FADD, and IDH1." (PMID 35911707, 2022). "ABCB1, BAX, BCL2, FADD, FAS, and several tumour protein families were identified as the genes responsible for such findings." (PMID 35884999, 2022). "From TCGA datasets, FADD, BIRC2/3, TNFSF10, and TNFRSF10B/C/D were overexpressed in tumor cases compared to normal." (PMID 33737574, 2021). "Western blot analysis showed that FADD was overexpressed in the tumours after VNP-FADD treatment; furthermore, the protein levels of FADD and cleaved caspase-3 were upregulated after the combined ADT-OH treatment." (PMID 31949127, 2020).
tumor (continued). "Mechanistic studies revealed that expression of various factors such as caspase-8, TNFα, RIP1, c-FLIP, FADD, cIAP1/2, and XIAP is essential for SM-mediated tumor cell death." (PMID 32325691, 2020). "We observed a decreasing expression level of HSPB8 and PRKN and an increasing expression level of EGFR, CDKN2A, FADD, and ITGA3 in tumor samples." (PMID 33456497, 2020). "ADT-OH treatment significantly increased the tumour necrosis area of B16F10 nc cells, but these effects were eliminated after FADD knockout." (PMID 31949127, 2020). "In cells with the expression of Beclin1 transiently reduced, knock down of CD95, FADD, or RIP1 almost abolished tumor cell killing." (PMID 32983965, 2020). "We have previously shown that knock down of CD95 or FADD, or over-expression of c-FLIP-s protected tumor cells from [curcumin + sildenafil] lethality." (PMID 29245915, 2017). "The cFLIPS·FADD·RIP1 or p22-FLIP·FADD·RIP1 complexes are reminiscent of a cytoplasmic complex, termed the ripoptosome, induced by treatments of human tumor cells that deplete or inhibit cellular inhibitor of apoptosis proteins." (PMID 26865630, 2016). "Another possible explanation is the common function of the simultaneously amplified genes of 11q13 (CTTN, FADD, CCND1, and FGF4) in tumor growth and invasion." (PMID 26194878, 2015). "The EVs isolated from tumor cells express, for example, FasL, MHC classes I and II, mRNA, miRNA, FADD, P-glycoprotein, MMPs, PS, and TF." (PMID 26380326, 2015). "Other targets of up regulated miRNAs in different treatment conditions also includes proteins that inhibit tumor progression, such as DNMT3A, FADD, pTEN, FOXO3, DDX20 and PA2G4 (EBP1)." (PMID 24387052, 2014). "Further assessment demonstrated that the expression of necroptosis-related genes, including FADD, MLKL, TLR2, PGAM, HMGB1, CXCL 1, TRAF2, and EZH2, was elevated in tumor tissue, while FAS, RIPK1, RIPK3, TLR3, TNFRSF, ALDH2, and NDRG2 were upregulated in normal intestinal tissues." (PMID 40959081, 2025). "According to the mRNA expression level in TCGA, FADD was related to lymph node metastasis, and ZBP1 might play a crucial role in tumor size as well as clinical stage." (PMID 38684755, 2024). "TNFR1, caspase-8, FADD, RIPK1, the LUBAC components, TRAF2 and cIAP1 have all been identified in genome-wide Crispr/Cas9 screens as important factors involved in the control of tumor development by CD8+ T cells and NK cells." (PMID 38020877, 2023). "Accordingly, we found a negative correlation between miR-675 and FADD in combined human liver RNA samples, which included normal and cirrhotic adult liver, fetal liver, and non-tumor and tumor samples of hepatic adenoma and HCC." (PMID 33499244, 2021). "Recently, we have investigated the anti-tumor effects of birinapant in HPV(−) HNSCC cells, and observed that cells retaining FADD/BIRC2 amplification and overexpression were sensitive to birinapant, and the effects were enhanced by death agonists TNFα or TRAIL23." (PMID 33737574, 2021). "On one hand, the stability of FADD in tumour cells would be increased by ADT-OH, and on the other hand, VNP-FADD would deliver FADD specifically to the tumour; thus, the antitumour effect would be more comprehensive and effective than either intervention alone." (PMID 31949127, 2020). "We also showed that FADD was more abundant in reconstituted NRF1 and K230R xenograft tumor tissues, indicating that the increased FADD may be responsible for the dramatic apoptosis in K230R tissues." (PMID 30833558, 2019). "Knock down of CD95/FADD suppressed [curcumin + sildenafil] lethality as did over-expression of c-FLIP-s, all, again, arguing that sildenafil utilizes the extrinsic pathway to kill tumor cells." (PMID 29245915, 2017).
tumor (continued). "Because 3LL cells failed to secrete cytokines in response to CD95L in vitro, we conclude that endogenous TRAIL/TRAIL-R induces secretion of CCL2 from tumor cells in a FADD-dependent manner and that this CCL2 is required to facilitate the accumulation of tumor-promoting myeloid cells in vivo." (PMID 28212753, 2017). "However, our in vivo genetic studies showing that double FADD/RIPK3 deficiency did not sensitize mice to AOM-induced colon tumorigenesis provided evidence that regulation of death receptor-induced programmed cell death is not critical for the tumour suppressing role of CYLD." (PMID 27561390, 2016). "DDX58 is a pattern recognition receptor that signals through FADD and MAVS and may contribute to the observed anti-tumor immune responses." (PMID 25952672, 2015). "On the other hand, TMZ, as a single agent, was not as effective as pG8-FasL/FADD in enhancing the survival of tumor bearing mice, albeit the difference between the median survival time for both treatment regimens was not statistically significant." (PMID 20942909, 2010). "Absence of FADD protein expression is a marker for tumor development and a prognostic factor for poor response to chemotherapy in humans." (PMID 19513126, 2009). "As a consequence, finding how to restore FADD protein expression in FADD-negative tumor cells represents a research field with potentially direct clinical applications." (PMID 15717929, 2005). "Absence of FADD allows co-expression of death receptors and ligands without inducing autocrine or paracrine apoptosis of tumor cells." (PMID 15717929, 2005). "Absence of FADD protein expression is a marker of tumor development in the mouse, and a prognostic factor for poor response to chemotherapy in humans." (PMID 15717929, 2005). "The fact that absence of FADD expression was found in different types of tumor cells both in mice and humans strongly suggested that absence of FADD contributed to tumor development." (PMID 15717929, 2005). "The combination of birinapant and irradiation or irradiation alone also significantly inhibited tumor growth in UM-SCC-11B xenografts overexpressing FADD and BIRC2, but not in UM-SCC-1 xenografts showing weaker growth and FADD/BIRC2 copy expression and heterozygous CASP8 mutation." (PMID 39458950, 2024). "The low FADD protein expression in most HPV(+) cells supports this hypothesis, which could explain why TRAIL or anti-TRAILR2/DR5 alone had minimal inhibitory effects on HPV(+) tumor cells." (PMID 33737574, 2021). "However, a direct link between miR-155 overexpression and FADD downregulation in those tumor samples has not been demonstrated." (PMID 31569512, 2019). "Altogether, this indicates that FADD may represent a tumor suppressor with positive and negative effects on T cell growth." (PMID 27556297, 2016). "The resultant balance between FADD-dependent apoptotic and non-apoptotic abilities may define the outcome of the tumor." (PMID 27556297, 2016). "Because the hazard score was associated with perineural invasion status of invasive ductal cancer of the breast, we may speculate that combination of TMEM16A, FADD and PPFIA1 expressions influence the invasiveness of the tumor cells and affect the ultimate prognosis of these cases." (PMID 24886289, 2014). "Therefore, many kinds of tumor cells are resistant or tolerant to TNF-induced apoptosis, although TNF may lead to apoptosis via the FADD-caspase pathway and the TRAF2-JNKK2 pathway." (PMID 23635099, 2013). "Lack of FADD protein confers survival/growth advantages in tumor cells." (PMID 19513126, 2009). "Since cytotoxic tumor infiltrating lymphocytes (TIL) use, among other mechanisms, death receptor-mediated cell death to kill pathological cells, tumor cells lacking FADD molecule expression may partially avoid immune attack." (PMID 15717929, 2005). "Indeed, lack of FADD protein can confer numerous advantages on pathological cells, which predominantly result in tumor survival/growth gain." (PMID 15717929, 2005).
tumor (continued). "Thus, absence of FADD expression in tumor cells must confer multiple resistance of these cells to death receptor cytotoxicity." (PMID 15717929, 2005). "Therefore, Fas signaling, particularly in the absence of FADD, can confer proliferative advantage on tumor cells." (PMID 15717929, 2005). "However, very little is known about the mechanisms leading to absent/low FADD protein expression in tumor cells." (PMID 15717929, 2005). "Since TRAIL-R2/FADD/pro-caspase-8 and cFLIP colocalize in intracellular membrane compartments even in the absence of TRAIL, cFLIPL downregulation in glutamine-dependent tumor cells could facilitate TRAIL-R2/DR5 aggregation and subsequent NF-kB activation, leading to IL-8 induction." (PMID 40683891, 2025). "Because FADD absence did not affect TNF-mediated cytokine secretion, and CD95L did not induce the secretion of cytokines from 3LL cells, it is unlikely that these death ligands are responsible for the decreased tumor burden observed in the syngeneic FADD-deficient 3LL model." (PMID 28212753, 2017). "FADD protein level was overexpressed, while ZBP1 protein level was nearly not expressed in tumor tissues." (PMID 38684755, 2024). "It was reported that when Daxx existed in the cytoplasm and nucleus in matrix protein mutant soluble tumor cells with vesicular stomatitis virus infection, Fas-mediated caspase activation relied on a Daxx–JNK signal rather than an FADD signal." (PMID 32782452, 2020). "In the absence of Beclin1, knock down of CD95, or FADD, or over-expression of c-FLIP-s or BCL-XL abolished tumor cell killing." (PMID 32983965, 2020). "Tumours treated with TH and MH showed no expression of FASLG and FADD (0% expression or positivity)." (PMID 28479926, 2017). "However, there are also some NRGs with CNV gain, such as FADD, FASLG, and no significantly difference in tumor and normal tissue." (PMID 36059470, 2022). "Tumours treated with HSA showed no expression of FASLG and FADD (0% expression or positivity)." (PMID 35386216, 2022). "Moreover, thymic lymphoblastic lymphomas were never observed in FADD-/- RAG-1+/+ or FADD-/- RAG-1+/- mice, demonstrating that absence of FADD expression was necessary but not sufficient to induce tumor development in this model." (PMID 15717929, 2005). "However, taking advantage of the fact that concomitant deletion of RIPK3 fully prevents skin lesion formation in mice with keratinocyte-restricted FADD knockout (FADDE-KO), we generated Sharpincpdm/cpdm;Ripk3−/− mice that also lacked FADD specifically in keratinocytes." (PMID 25443631, 2014).